BECN1 (beclin 1)
Diseases named in the same sentence as BECN1 in open-access papers (continued):
Sharing a sentence is not in itself a finding about the gene and the disease.
infection (177 papers, 2008 to 2026). The state of being infected such as from the introduction of a foreign agent such as serum, vaccine, antigenic substance or organism. "This contrasted with the reduced association of BCL2 with BECN1 after infection of germ-free wild-type mice." (PMID 39602254, 2024). "We performed acute T. cruzi infections in Beclin-1 heterozygous mutated mice (Bcln1±, Bcln KD), which displays a reduced autophagic response, comparing the course of the infection in the controls Bcln1+/+ (Bcln WT) mice." (PMID 30829115, 2019). "We have performed an acute model of infection on the autophagic deficient Beclin-1 heterozygous knock-out mice (Bcln±) and compared to control Bcln+/+ animals." (PMID 30829115, 2019). "Desipramine inhibits infection, yet Beclin 1, TGN46, and BODIPY ceramide associated with the ApV in treated cells." (PMID 30902833, 2019). "We found that Beclin 1-deficient cells supported lower levels of Bm16M infection than controls." (PMID 29732320, 2018). "Moreover, compared to Becn1+/+ mice, infection of Becn1+/− mice markedly enlarged liver-associated infectious foci." (PMID 27694929, 2016). "At the same time, inhibition of Beclin-1 function disrupts cellular homeostasis and exacerbates inflammatory damage at the site of infection." (PMID 41562082, 2025). "The data indicated that at the mRNA and protein level, G. parasuis induced the LC3B expression level and downregulated P62 and Beclin-1 expression levels in the spleen from the infection group, in contrast with the control group (p < 0.001)." (PMID 40427533, 2025). "Inhibition of autophagy after infection resulted in increased p62 levels and decreased Beclin-1, ATG7, and ATG5 levels, similar to the response to IFITM3 knockdown, whereas overexpression of IFITM3 had the opposite effect." (PMID 40681213, 2025). "Levamisole treatment reduced the LC3B mRNA and protein levels, upregulated Beclin-1 mRNA and protein levels, and increased P62 mRNA expression level in the spleen, in contrast with the infection group (p < 0.01)." (PMID 40427533, 2025). "Following mechanistic investigations demonstrated that HBHA treatment significantly attenuated BCG-induced LC3-II and Beclin-1 expression compared to infection alone." (PMID 41209015, 2025). "CCR2 inhibition reduced ESAT-6 expression and restored Beclin-1 levels in lung tissue, alleviating inflammation and injury during late-stage infection." (PMID 41562082, 2025). "The autophagy-related marker proteins LC3B, ATG5, and BECN1 were upregulated post-infection, whereas SQSTM1 was downregulated, indicating that FAdV-4 infection enhances autophagic flux and induces complete autophagy." (PMID 40130861, 2025). "Our results indicate that after the infection autophagic genes [Beclin-1 (p ≤ 0.03), UVRAG (p ≤ 0.03), Atg5 (p ≤ 0.01), Atg12 (p ≤ 0.01) and Atg16L (p ≤ 0.03)] are upregulated in contrast to the control group." (PMID 39845048, 2024). "Disruption of Beclin-1 can alter cytokine production and immune cell function, impacting inflammatory conditions and infection defense." (PMID 39650649, 2024). "SQSTM1/p62 protein, a marker of autophagy execution, is accumulated in GD-SH-01-infected NA cells with an increase in infection time, while the expression level of BECN1, a protein critical for autophagosome formation, is significantly upregulated." (PMID 38247875, 2024). "To assess the impact of Beclin-1 on SARS-CoV-2 infection we depleted cells of Beclin-1 using a specific siRNA followed by infection with either the reporter virus or wild-type virus." (PMID 36622177, 2023). "The reduced infectivity of EcoHIV in Becn1+/− mice indicates that the infection efficiency is different between the two strains." (PMID 37766329, 2023). "After OVV-BECN1 infection, translated Beclin-1 activates downstream signalling molecules, resulting in autophagosome formation and the induction of autophagic cell death." (PMID 37615308, 2023).
infection (continued). "The effects If iAs3+ on LC3 and Beclin-1 protein expression in LX-2 cells after plasmid infection were analyzed." (PMID 37505544, 2023). "The SQSTM1 transcript was more rapidly and more intensively induced upon CCHFV infection and BECN1 expression was more rapidly augmented as well." (PMID 36298785, 2022). "In another set of experiments, we performed primary cultures of BMM obtained from Beclin-1 heterozygous knockout mice (KD) and studied the level of infection in the presence of UA in comparison with cells obtained from WT animals." (PMID 36004334, 2022). "Accordingly, in vivo infection with MERS-CoV-MA-Δ4b increased the expression of autophagy mediators BECN1, ATG3 and LC3A." (PMID 36129908, 2022). "Examined at 48 h post infection, a 10-fold or more decreases in colony formation were observed in mice with Beclin-1 activation, either Becn1F121A/F121A mice or TB peptide–treated mice, when compared with that in the WT counterparts." (PMID 34211859, 2021). "NS1 is also thought to interact with Beclin-1, an autophagy-related protein, to prevent apoptosis and increase viral replication in the early stages of infection." (PMID 34207516, 2021). "This study found significant accumulation of autophagic factors LC3 and p62 and a slight increase in the beclin-1 level of GBM cells during PeV-A3 infection periods." (PMID 34899705, 2021). "The elevated levels of caspases in the late infection stages degrade Beclin-1, leading to apoptosis." (PMID 34207516, 2021). "Overall, the data shows significant infection throughout gestation in both Becn1 reduced and Becn1+/+ pregnant dams infected with ZIKV." (PMID 32498399, 2020). "On the other hand, the LC3-II accumulation decreased within 24 to 72 h post-infection and viral tilters were reduced by 0.56 logs (p < 0.05) at 24 h post-infection in Beclin-1 knockdown cells compared with control cells." (PMID 33352639, 2020). "Our study suggests a novel mechanism whereby NS1 preserves Beclin-1 for maintaining autophagy to antagonize early cell apoptosis; however, elevated caspases trigger apoptosis by degrading Beclin-1 in the late stage of infection." (PMID 33352639, 2020). "Here, we used a hemizygous (Becn1+/−) and wild-type (Becn1+/+) mouse model to further decipher the role of autophagy in the infection and pathology of the epidemic human ZIKV strains, 2015/Honduras (R103451), during pregnancy and birth." (PMID 32498399, 2020). "We found that the Beclin-1 protein expression was significantly decreased after the infection of the S.E-WT expressing AvrA." (PMID 32362899, 2020). "Mixed glial cultures were permissive to infection, albeit higher number of plaques were detected in Becn1+/− glia infected with ZIKV." (PMID 32498399, 2020). "In response to various stimuli, including nutrient starvation, organelle damages, and pathogen infection, cytosolic materials are sequestered by expanding isolated membrane via activation of Beclin-1/Vps34 complex followed by LC3 processing." (PMID 30619194, 2018). "Control and Beclin 1-KD cells were infected with C. burnetii and following 48 h of infection, the cells were fixed, subjected to immunofluorescence against Gal3 and analyzed by confocal microscopy." (PMID 28484683, 2017). "On the other hand, the infection of mice with the WT showed elevated expression of autophagy-related proteins, Beclin-1 and LC3, which was prevented by infection with the vvhA mutant." (PMID 27250250, 2016). "Once HIV establishes a productive infection, Nef binds BECN1 resulting in MTOR activation, TFEB phosphorylation and cytosolic sequestration and the inhibition of autophagy." (PMID 26115100, 2015). "Once HIV establishes a productive infection, Nef inhibits autophagy by binding BECN1 resulting in TFEB phosphorylation and cytosolic sequestration." (PMID 26115100, 2015). "The elevated expression of Atg5 and beclin-1 by D39 infection was significantly decreased by NAC treatment." (PMID 26683708, 2015).
infection (continued). "Upon ARV S1133 infection, the −644 to +197 regulatory region of the Beclin-1 gene showed a higher luciferase activity than the −277 to +197 control region reporter, and the −58 to +197 region revealed a negligible luciferase response." (PMID 25944062, 2015). "During permissive infection, Nef binds BECN1 resulting in mammalian target of rapamycin (MTOR) activation, TFEB phosphorylation and cytosolic sequestration, and the inhibition of autophagy." (PMID 26115100, 2015). "Infection of F11 cells with beclin 1 shRNA lentivirus resulted in a significant decrease in SEAP activity compared to cells infected with the control virus." (PMID 26692002, 2015). "In this regard, the mRNA of this gene increased in THP1-Vector cells at 72 h post-infection, and the expression of hAIM further increased Beclin 1 mRNA levels 1.5-fold." (PMID 24223991, 2013). "Consistent with the accumulation of LC3-II in HIV-infected CD4+ T cells, on day 5 post-infection, Beclin 1 protein level was higher in HIV-infected CD4+ T cells than in uninfected CD4+ T cells." (PMID 23658518, 2013). "During infection, HIV down regulates Beclin-1 and microtubule-associated protein 1 light chain 3B (LC3B)-II, reducing both basal autophagy and the numbers of autophagosomes per cell." (PMID 22589721, 2012). "These include Ifi27, Ifih1, Irf7 and Oas1b which were upregulated at 72 hr and 96 hr post infection except Becn1 that was over-expressed only at 72 hr post infection, and Spn which was over-expressed at all time points." (PMID 18558011, 2008). "In conclusion, this study preliminarily elucidates the mechanism by which cpBVDV/ncpBVDV infection-induced autophagy selectively degrades MAVS via BECN1–MAVS interaction, thereby suppressing the RIG-I–MAVS signaling pathway and impairing antiviral innate immunity." (PMID 41363843, 2026). "Infection of C. parvum leads to up-regulation of Beclin-1, ATG7, and ATG5." (PMID 40681213, 2025). "Additionally, it was confirmed that changes in the levels of AMPK and Beclin-1 were evident from the early stage of infection." (PMID 39998213, 2025). "RBAC can also stimulate cytokine secretion in macrophages, especially TNF-α and IL-6, to initiate inflammation during infection and activate autophagy-related proteins (Beclin-1, Atg5, Atg12, Atg16L) for clearing cellular debris and regulating inflammatory responses." (PMID 37687141, 2023). "To determine whether LM induced an increase in autophagy-related gene expression in B16F10 cells, we detected the relative expression of Atg3, Atg5, Beclin-1, and p62 mRNA at 4 h post-infection by real-time PCR." (PMID 36838373, 2023). "NS1 interacts with the autophagy-associated protein Beclin-1 during DENV infection to attenuate Beclin-1 cleavage and thereby promote autophagy to prevent apoptosis and increase viral replication in the early stages of infection." (PMID 37821951, 2023). "Transient depletion of Beclin-1, which functions as a scaffold in forming a multiprotein assembly during autophagy initiation and nucleation, and is a known target of γ1 34.5, obstructed the infection." (PMID 36622177, 2023). "Beclin-1 expression began to decrease 24 h after infection and continued to decline over 72 h." (PMID 37026095, 2023). "It promotes the downregulation of PI3KC3, Beclin 1, and the mammalian target of rapamycin (mTOR), which, in turn, promotes autophagy, lysosomal degradation, and antigen presentation—essential components of the pre-infection defense mechanism." (PMID 37299555, 2023). "In a paper studying the effect of autophagy enhancer on infection, Tat-beclin 1 reduced replication of Listeria monocytogenes and viruses such as Sindbis virus, chikungunya virus, West Nile virus and HIV in vitro and improved clinical outcome of such infections in vivo." (PMID 35237600, 2022). "Moreover, Beclin 1, which is essential for both autophagy and lysosomal enzyme transport, was increased after infection with S. lutetiensis." (PMID 35178153, 2022).
infection (continued). "The autophagic markers, particularly autophagy-related gene 6 (Beclin-1), microtubule-associated protein 1A/1B-light chain 3 (LC3) and p62, were observed to be differentially expressed after infection with Salmonella indicating an activated autophagy in ATC cells." (PMID 36118522, 2022). "In addition to the protective aspects, host infection by SARS-CoV-2 acts to inhibit Beclin-1 and autophagosomal degradation, which can be reversed by increasing SPD." (PMID 35684363, 2022). "Autophagosome‐related structures including sequestering phagophores, typical double‐membrane autophagosomes and autolysosomes were observed by transmission electron microscopy following infection of 3T3‐L1 mature adipocytes with Becn1 overexpression lentivirus." (PMID 34085745, 2021). "At E17 (8 days post-infection), maternal placenta and other organs removed postmortem from Becn1+/+ and Becn1+/− dams, showed a high level of viral RNA in the placenta, followed by the spleen, liver, heart and the lowest titer was detected in the brain, irrespective of mice strain." (PMID 32498399, 2020). "Therefore, it is suggested that DENV infection causes a low level of activated caspases in the early infection stage, which still allows DENV NS1 to protect Beclin-1 from caspase-mediated cleavage." (PMID 33352639, 2020). "Beclin-1 protein levels were reduced with AvrA present strain infection." (PMID 32362899, 2020). "In contrast, S.E-AvrA mutant strain infection maintained Beclin-1 protein expression." (PMID 32362899, 2020). "Similar results were obtained after infection of autophagy deficient cells lacking Beclin 1 or LC3B." (PMID 31306441, 2019). "As expected, ATG5, Beclin-1, ATG7 and ATG16L1 deficiency led to impaired conversion of endogenous LC3-I to LC3-II and decreased number of LC3 puncta following SH0165 infection." (PMID 31106159, 2019). "We also tested whether several host autophagy-related components, including Atg1 (ULK1), Atg2, Atg18 (WIPI1), Atg9 and Beclin 1, conferred susceptibility to Bm16M infection via CFU assay and image-based host cell infection analysis." (PMID 29732320, 2018). "During Sindbis virus infection, beclin 1 expression was upregulated that may result in xenophagy (a selective autophagy) of Sindbis virus to defend the infection." (PMID 28475412, 2018). "Moreover, during a time course (48 h) of Bm16M infection, less Beclin 1-positive BCVs were found in the Ern1mut/mut BMDMs, indicating that Beclin 1 recruitment by BCVs is in an IRE1α-dependent fashion." (PMID 29732320, 2018). "Beclin 1 protein levels increased ~1.76-fold in AdBeclin 1-infected cells and was ~2-fold down in AdshBeclin 1-infected cells related to AdLacZ control cells after 36 h of infection." (PMID 28151484, 2017). "Notably, cysteamine was not capable of increasing the intracellular clearance of P. aeruginosa (P>0.5) in BMDMs from Becn1+/− upon infection." (PMID 28079883, 2017). "In addition, the LC3 recruitment to damaged endosomes containing GAS (Galectin-3-poisitve GAS) was suppressed in Beclin 1 KO cells at 2 and 4 h post-infection in comparison with that of wild-type cells." (PMID 28085926, 2017). "In this study, we demonstrated that ARV S1133 caused autophagy and apoptosis in Vero and DF1 cells, which was accompanied by the activation of the Beclin-1 promoter in the early to middle stages, and induction of caspase-3 expression in the middle to late stages of infection." (PMID 25944062, 2015). "Infection of primary forebrain neurons resulted in efficient knockdown of beclin 1 by 75 % (, b)." (PMID 26692002, 2015). "ARV S1133 also activated the Beclin-1 promoter in the early to middle stages of infection." (PMID 25944062, 2015). "Our findings demonstrate that infection with either cpBVDV or ncpBVDV markedly enhances cellular autophagic activity, as evidenced by significant upregulation of the autophagy-related proteins BECN1 and LC3, which promotes autophagosome formation, consistent with our recent report." (PMID 41363843, 2026).
infection (continued). "Nonetheless, we confirmed that activation of Beclin-1 either genetically by a forced expression of activation mutant Becn1F121A or pharmacologically by an activating peptide, TB-peptide, indeed dramatically enhanced autophagy signaling in the lung under the condition of infection." (PMID 34211859, 2021). "Thus, we determined whether the protein level of Beclin-1 was changed by the infection with the different S.E strains." (PMID 32362899, 2020). "Thus, we hypothesized that Beclin-1 may be protected from caspase-triggered degradation by interacting with viral factors in the early stage of infection." (PMID 33352639, 2020). "Consistent with this, Western blot analysis showed increased protein levels of BECN1 and lipidated LC3B-II upon cpBVDV infection." (PMID 41363843, 2026). "In this study, infection by C. parvum up-regulated the ratio of LC3B II to LC3B I, p62, Beclin-1, ATG7, and ATG5." (PMID 40681213, 2025). "The same effect was observed for Beclin-1 expression, which increased at early time points (3, 6, and 12 h) and decreased post-infection (24 and 36 h), suggesting that DENV regulates Beclin-1 expression during the early stages of infection." (PMID 41471247, 2025). "IFITM3 overexpression up-regulated LC3B II/LC3B I, Beclin-1, ATG7, and ATG5, but down-regulated p62 during infection." (PMID 40681213, 2025). "In CSFV cell infection experiments, the high expression of autophagy markers ATG5 and BECN1 (Beclin 1), along with the degradation of SQSTM1 (Sequestosome 1), indicates that CSFV infection triggers a complete autophagy response." (PMID 40869159, 2025). "The infection stage group had higher content of PCT, TNF‐α, and IL‐6 and lower content of Beclin‐1 and LC3 than the infection control group (p < .001)." (PMID 38577990, 2024). "Compared with the infection control group, the expression of Beclin‐1 and LC3 in the infection stage group were sharply lower (p < .001)." (PMID 38577990, 2024). "The results of this study showed that the content of Beclin‐1 and LC3 largely decreased in DFU patients, and gradually decreased with the aggravation of infection." (PMID 38577990, 2024). "In comparison with the control group, the expression of Beclin‐1 and LC3 in the infection control group were slightly lower (p > .05), while the levels of PCT, TNF‐α, and IL‐6 in the infection stage group were significantly higher (p < .05)." (PMID 38577990, 2024). "Of note, infection by T. gondii significantly inhibited starvation-induced transcription of autophagy-related genes (i.e., ULK1, BECN1, PINK1, GABARAPL2, SQSTM1, and NBR1), as compared to uninfected serum-starved HFF cultures (i.e., “Control”)." (PMID 37387601, 2023). "Peritoneal cells derived from Becn1+/- animals and RAW macrophages treated with autophagy inhibitors displayed higher levels of infection compared to controls." (PMID 37064813, 2023). "Lastly, we evaluated the response of combined ART on viral load in Becn1+/− and C57BL/6J control mice after infection with EcoHIV." (PMID 37766329, 2023). "Beclin 1 and ATG5 proteins were significantly enhanced in ncp BVDV2‐infected cells compared to mock infection, whereas their expressions were decreased in 3‐MA‐treated ncp BVDV2‐infected cells." (PMID 36533845, 2023). "Subsequent infection of both cell types with M. bovis for 6 and 24 h revealed that the down-regulation of GBP2b downregulated the expression levels of LC3-II and Beclin-1 in both types of cells." (PMID 35531887, 2022). "After infection with HSV-1, BECN1 interacts with cGAS, thus altering its nucleotidyltransferase function and triggering the autophagic machinery." (PMID 33763351, 2021). "We next focused on the early stage of infection, and data confirmed that much more LC3-II and Beclin 1 were assessed in macrophages infected with STM-ΔspvC than in those infected with S. Typhimurium carrying spvC." (PMID 34335562, 2021).